MTOR (mechanistic target of rapamycin kinase)
Diseases named in the same sentence as MTOR in open-access papers (continued):
Sharing a sentence is not in itself a finding about the gene and the disease.
cancer (continued). "Since mTOR inhibitor induced phosphorylation of eIF4E in a Mnk-dependent manner, combination of mTOR inhibitor and Mnk inhibitor is a promising strategy to improve the efficacy of mTOR inhibitor in human cancers." (PMID 27050281, 2016). "When the mTOR-mediated phosphorylation of 4EBP1 was blocked in MYC driven cancers by MLN0128, which specifically blocks the mTOR active site by inhibiting 4EBP1 phosphorylation, it specifically induced significant apoptosis in the MYC driven pre-tumor B cells, while sparing the wild type B cells." (PMID 28025559, 2016). "The phosphatidylinositol-4,5-bisphosphate 3-kinase (PI3K)/serine/threonine-specific protein kinase (Akt)/mammalian target of rapamycin (mTOR) pathway regulates cell proliferation and cell growth and is often stimulated in cancer, which makes it an important target pathway for cancer therapies." (PMID 26956874, 2016). "Numerous cancer cells depend on the mTOR pathway for efficient cellular proliferation." (PMID 27231932, 2016). "The role of the AMPK/mTOR pathway in the progression of cancer has also been related to NF-κB." (PMID 26892992, 2016). "The PI3K/AKT/mTOR pathway is one of the major signaling pathways that regulate cell growth, proliferation, metabolism, and survival and is one of the most commonly deregulated pathways in cancer." (PMID 26657290, 2016). "Presence of NF1 germline mutation suggests the patient may benefit from anti-MEK or anti-mTOR agents that are commercially available for other cancer indications." (PMID 27245685, 2016). "The PI3K/AKT/ mTOR pathway is one of the most deregulated pathways in human cancer." (PMID 27351224, 2016). "A growing body of evidences suggests that miRNAs may play a crucial role in cancer therapy and diagnosis, which mostly performed through the mTOR signaling pathway." (PMID 27540517, 2016). "For example, while mTOR and E2F1 are the top-ranking oncomodules associated to mutations of MLL2 in HNSC, we found that oncomodules in the MEK/AKT1 axis are top-ranking in association to NSD1 mutations in the same cancer type." (PMID 27095575, 2016). "Interestingly, not only proton pump inhibitors but also mTOR inhibitors such as rapamycin or rapamycin analogues (rapalogs), used in the treatment of cancer have shown to decrease lactate production by tumor cells increasing extracellular pH." (PMID 27716623, 2016). "Regardless of different cancer types, mTOR-pathway-activating mutations confer sensitivity to everolimus." (PMID 26859683, 2016). "It is critical to understand the molecular mechanisms of exhibiting enhanced inhibitory effects on NSCLC cells by combination of mTOR and Mnk inhibitors, and which will help us to develop new therapy strategies to overcome resistance in mTOR-targeted cancer therapy." (PMID 27050281, 2016). "A valuable example is the effect of mTOR inhibitors on protein synthesis in cancer cells." (PMID 26802582, 2016). "Existing evidences have shown that a number of mTOR inhibitors could activate autophagy in various cancer cells, which serves as a pro-survival factor counteracting cancer cell death." (PMID 27385099, 2016). "However, most studies that targeted the mTOR pathway in cancer therapy have focused on allosteric mTOR inhibitors." (PMID 27031247, 2016). "A recent report suggested that mTOR-inhibitors differentially influence mitochondrial dynamics in cancer cells which might affect therapeutic efficiency of mTOR-targeted therapy." (PMID 26940200, 2016). "Inhibition of mTOR by rapamycin and its analogs appears to be efficient in cancer therapies." (PMID 27517315, 2016).
cancer (continued). "However, when the PI3K/Akt/mTOR pathway becomes hyperactive, the induction of the de novo lipogenesis is a requisite for supporting cancer cell growth." (PMID 28115925, 2016). "Everolimus is a selective inhibitor of mTOR approved by FDA for use in cancer treatment." (PMID 27533461, 2016). "Indeed, de novo lipogenesis is activated downstream of the Akt/mTOR pathway, one of the most common signaling pathways altered in cancer." (PMID 28115925, 2016). "BEX2 expression could possibly be modulated by the aberrantly activated mechanistic target of rapamycin (mTOR) in cancer cells." (PMID 27297407, 2016). "The PI-3K/mTOR pathway is over-activated in many cancer cells." (PMID 26814436, 2016). "Blocking mTOR activation by an mTOR inhibitor, such as everolimus or temsirolimus, exhibits an anti-neoplastic effect and is approved by the Food and Drug Administration and the European Medicines Agency for the treatment of limited types of cancers." (PMID 27462867, 2016). "mTOR is a serine/threonine protein kinase that controls cell growth in response to nutrients and growth factors and it has been found to be frequently deregulated in cancer." (PMID 26756219, 2016). "Although BCAAs are increasingly used as a treatment for cancer cachexia, others have shown that BCAA supplementation caused significant enhancement of tumor growth via activation of mTOR/AKT pathway, which is consistent with our results that BCAAs are up-regulated in HCC." (PMID 26030804, 2015). "Recently, the PI3K/Akt/mTOR pathway has been identified as an important signalling pathway to tightly modulate many cellular events including the physiological activities of mitogenic or oncogenic factors, leading to the genesis of many human cancers." (PMID 26022660, 2015). "Thus, inhibition of the PI3K/AKT/mTOR signaling axis is one of the mechanisms by which HDACIs reduce the proliferation and induce apoptosis of cancer cells." (PMID 26287365, 2015). "Since activities interplaying with signaling pathways of PI3K/AMPK/AKT/mTOR, and MAPKs can promote cancer chemoresistance and radioresistance, we assessed whether 21α-MMD affects these pathways in A549-PacR cells." (PMID 26098947, 2015). "Our results show that HRAS mutations in cancer activate the RAS and mTOR pathways which might serve as a therapeutic option for patients with HRAS mutant tumors." (PMID 26544513, 2015). "We validated in vitro that PRL-3 overexpression could induce mTOR phosphorylation in six out of the nine human cancer cell lines tested." (PMID 26597054, 2015). "Also, higher consumption of glutamine in cancers is used for EAAs (essential amino acids) exchanges that are required for cell growth and mTOR (mammalian target of rapamycin) activation, which then initiates protein translation and cell growth." (PMID 26402672, 2015). "Src kinase is an important regulator for mTOR signaling in cancer." (PMID 26582057, 2015). "Inhibitors of the PI3K/AKT/mTOR pathway hold promise for treating cancer, and may be most effective when used in combination with other agents." (PMID 25576920, 2015). "The PI3K/Akt/mTOR pathway is involved in providing stimulation for cell proliferation, inhibition of apoptosis and it is has been assessed that this pathway is dysregulated in at least 50% of all cancer types." (PMID 26451606, 2015). "In the BOLERO-2 trial, BC patients with bone involvement who received Everolimus had a delayed tumor progression in the skeleton as a result of direct OC suppression through the inhibition of mTOR, in addition to the general suppressor effect on the cancer cells." (PMID 26468083, 2015). "Inhibition of mTOR alone results in cancer relapse due to up-regulation of PI3K activity." (PMID 26451606, 2015). "Activation of the PI3K/Akt/mTOR signaling pathway is well established to be related to tumorigenesis and cancer progression in many types of tumors, which could further contribute to acquired resistance to various anti-neoplastic agents." (PMID 25886409, 2015).
cancer (continued). "Interest into targeting the phosphoinositide 3-kinase, AKT, and mammalian target of rapamycin (PI3K/AKT/mTOR) signaling network in cancer has increased by the recent disclosure that PIK3CA of the PI3K pathway is the second most frequently mutated gene in cancer." (PMID 26056603, 2015). "Notably, mTOR is a critical effector in cell-signaling pathways commonly deregulated in human cancers and overexpression of the components involved in the PI3K/AKT/mTOR pathway has been shown to induce malignant transformation." (PMID 26273626, 2015). "We were intrigued by the finding that depletion of Glutamine tRNA synthase/QARS gives strong inhibition of S6-P in MIA PaCa-2 cells and is also high on the list of genes whose depletion affects the proliferation of the Achilles cancer cell cohort in a manner similar to mTOR depletion." (PMID 25790369, 2015). "Since the aberrant activity of the PI3K/AKT/mTOR pathway was commonly observed in cancers, and mTOR inhibitors were used in clinical trials, our current comprehensive results offer an opportunity to discern the molecular mechanism involved in inhibition of the signaling pathway in MPN." (PMID 26275051, 2015). "Specifically, ATP-site inhibitors of mTOR are emerging as potential cancer therapeutics." (PMID 25797255, 2015). "Similarly, the PI3K/AKT/mTOR survival pathway regulates diverse processes such as cell proliferation, differentiation, metabolism, cytoskeletal organization, apoptosis, and cancer-cell survival." (PMID 25955301, 2015). "Numerous investigations have demonstrated that the PI3K/AKT/mTOR signaling is commonly over-activated and plays an important role in the stimulation of proliferation, survival, metastasis, and drug-resistance in many cancer types." (PMID 26325371, 2015). "Besides the use of mTOR inhibitors in treating cancer, rapamycin and other rapalogs were also reported to have indirectly cancer-preventive effects in human by slowing aging." (PMID 26259252, 2015). "In addition, introduction of cells with constitutively active AKT1 significantly rescued the inhibitory effect of RY-2f, clearly indicating that the anti-cancer effect is dependent on suppression of the PI3K/AKT /mTOR pathway." (PMID 26325371, 2015). "The activation of Akt results in the phosphorylation and activation of mTOR in cancer and PKD." (PMID 26110849, 2015). "Currently, several inhibitors for mTOR have been approved for treating patients with cancers." (PMID 25924236, 2015). "Also, the contribution of mLST8 to carcinogenesis and/or progression of human cancers, particularly those in which mTOR pathways are deregulated, remains uncharacterized." (PMID 25906254, 2015). "A critical role of mTOR signaling in cellular function has been reported mainly in cancer cells." (PMID 26120832, 2015). "The distinct functions of mTOR in cancer and normal cells may be due to structural changes in mTOR complexes that are dependent on mLST8 levels." (PMID 25906254, 2015). "Other studies in cancer cells demonstrated that targeting AMPK/mTOR inhibits lipogenesis." (PMID 26002551, 2015). "Integrin β1 is regulated by PI3K/AKT/mTOR signaling in other cancers." (PMID 26337467, 2015). "Rapamycin, an inhibitor of mTOR, has been widely used as an immunosuppressant and anti-cancer drug." (PMID 26248290, 2015). "Dysregulation of the PI3K/Akt/mTOR signaling pathway is evident in many types of cancers and may affect both tumorigenesis and therapy resistance." (PMID 25815458, 2015). "In summary, these results suggested that suppressing PI3K/AKT/mTOR pathway may be a general mechanism by which Rapamycin enhanced the anti-cancer effect of Dasatinib in NSCLC cells." (PMID 26061184, 2015). "Moreover, sporadic mutation or dysregulation of protein kinase B and the tuberous sclerosis complex, which are upstream components of the mTOR pathway, are frequently altered in cancer." (PMID 25923415, 2015).
cancer (continued). "They showed that prevention or disruption of the activation of Akt and eIF4E enhanced rapamycin-mediated growth inhibition, indicating that the induced activation of Akt and eIF4E survival pathways counteracts the mTOR inhibitor's effect on the growth of human cancer cells." (PMID 26351512, 2015). "Therefore, targeting of the mTOR pathway is an attractive strategy for cancer treatment and several mTOR inhibitors, including AZD8055 (AZD), a novel dual mTORC1/2 inhibitor, are currently in clinical trials." (PMID 26221145, 2015). "In this review, we summarize the frequent amplification of PI3K/Akt/mTOR signals in HPV-induced cancers and discuss how HPV oncogenes E6/E7/E5 activate the PI3K/Akt/mTOR signalling pathway to modulate tumor initiation and progression and affect patient outcome." (PMID 26022660, 2015). "These cancers were highly sensitive to treatment with dual PI3K/mTOR inhibition." (PMID 26436951, 2015). "Mechanically, increasing autophagic flux by inhibiting the PI3K/Akt/mTOR pathway may promote the apoptosis of cancer cells." (PMID 25743109, 2015). "mTOR is an intracellular protein, playing a major role in protein synthesis and influencing the cell growth, differentiation and apoptosis: this pathway is unregulated in many cancers, leading to the permanent activation, often under the influence of IGF1R." (PMID 26541413, 2015). "While it is well established that metformin can activate AMPK, emerging evidence shows that metformin may modulate cancer activities, and particularly the mTOR pathway, through AMPK-independent mechanisms." (PMID 25867026, 2015). "For example, mTOR pathway has been found activated in a wide variety of diseases including cancer." (PMID 26460955, 2015). "The effectiveness of inhibiting both ERK1/2 and mTOR was examined in other cancers." (PMID 25815458, 2015). "Moreover, since mTOR exists as two complexes, mTORC1 and mTORC2, the role of mTORC2 in cancer and in the DNA damage response is less well explored." (PMID 25460505, 2015). "It has been hypothesized that LAT1 provides the essential amino acids to enhance cancer cell growth via mTOR-stimulated translation, and that ASCT2 maintains the cytoplasmic amino acid pool to drive LAT1 function." (PMID 26402672, 2015). "Interestingly, we discovered that most of the cancer-related signaling pathways reported previously such as Notch, mTOR and Hedgehog were activated in GC based on our data." (PMID 25928635, 2015). "Moreover, the crosstalk between the pathways was further supported by evidence that combination treatments of SMO inhibitors and mTOR inhibitors showed synergistic effect on cancer cell inhibition 14,19." (PMID 26218750, 2015). "Additionally, cancer metastasis is inhibited by the inhibition of MMP-9 through blocking mTOR signaling." (PMID 26202311, 2015). "Further analyses of mLST8-mediated regulation of mTOR pathways may provide new targets for therapeutic intervention in a wide variety of human cancers." (PMID 25906254, 2015). "Phosphorylated mTOR can promote the proliferation, motility, and survival of cancer cells." (PMID 25957503, 2015). "The PI3K/AKT/mTOR signaling cascade plays a central role in cell biology, including proliferation, survival, metabolism, angiogenesis and genome stability, and this cascade is deregulated in diverse human cancers." (PMID 25857298, 2015). "Additionally, mTOR (mammalian target of rapamycin) inhibition induces activation of Akt in cancer cell lines and patient tumors." (PMID 26402468, 2015). "The mTOR signaling pathway is also believed to be a valuable target for cancer therapy." (PMID 26307246, 2015).
cancer (continued). "Therefore, mTOR has been a molecular target of cancer therapy, and its inhibitors (such as rapamycin and its analogs) are used as molecular target drugs." (PMID 25887043, 2015). "Aberrations in the mTOR (mechanistic target of rapamycin) axis are frequently reported in cancer." (PMID 26255626, 2015). "Thus, no consistent conclusion has been drawn about the prognostic significance of mTOR/p-mTOR in other cancers." (PMID 25680114, 2015). "In particular, AMPK activation opposes tumor progression in several cancer types through inhibition of tumor growth-stimulating mammalian Target of Rapamycin (mTOR), and to down-regulation of cyclins and cyclin dependent kinases (CDKs) to inhibit cell-cycle progression." (PMID 26265439, 2015). "While suppression of the immune reactivity against cancer cannot be completely avoided with an immunosuppressive drug, mTOR inhibitors have a unique potential to both suppress an immune response to the organ allograft and promote mechanisms that can potentially inhibit tumour development." (PMID 25699174, 2015). "Finally, PIK3CA/AKT/mTOR signaling is ubiquitously deregulated in cancer, and it is apparent that there is significant crosstalk between this pathway and that related to androgens." (PMID 25595907, 2015). "This function might be crucial for the growth and survival of cancer cells, especially for those resistant to the allosteric mTOR inhibitor rapamycin." (PMID 26302180, 2015). "Numerous efforts have been made to develop PI3K/AKT/mTOR targeted therapies for cancer treatments." (PMID 26421002, 2015). "Considering that p-Akt may mediate irradiation-induced VEGF upregulation, it is conceivable that rapamycin, blocking Akt/mTOR pathway, combined with radiotherapy may serve as a novel treatment strategy for cancer through better targeting tumor vasculature." (PMID 26431328, 2015). "Whether IL-24-mediated inhibition occurs via the AKT/mTOR pathway in human cancers of different origins is unknown and should be investigated." (PMID 26009991, 2015). "Recent studies could demonstrate that in TGF-β-induced EMT, activation of mTOR signalling is required for tumour cell motility and cancer invasion." (PMID 25811030, 2015). "The PI3K/Akt/mTOR signaling axis plays a critical role in regulating cell proliferation, apoptosis, angiogenesis and metastasis, which is central to the development and maintenance of cancer cells." (PMID 25793983, 2015). "Therefore, the effect of mTOR on the radio-resistance of cancer cells under hypoxia was evaluated using the mTOR inhibitor temsirolimus." (PMID 25887043, 2015). "Moreover, eIF4E is a key event downstream of ras and phosphatidylinositol 3-kinase/protein kinase B/mammalian target of rapamycin (PI3K/AKT/mTOR) signaling pathway, which are frequently activated in a diverse range of human cancer." (PMID 26078354, 2015). "In addition to its effects on glucose metabolism, it ultimately inhibits mTOR in cancer cells and leads to growth arrest and apoptosis." (PMID 25504439, 2015). "Collectively, these findings suggest that mTOR plays a pivotal role in cell adhesion; and mTOR inhibitors may have a potential not only for treatment of cancer, but also for prevention of cancer metastasis." (PMID 25762619, 2015). "RPS6, 70 kDa, polypeptide 2 (RPS6KB2) and PTEN were strongly associated with the activation of the mTOR signaling pathway in cancer, while mTOR pathway activation demonstrated higher expression of RPS6K, S6, 4E-BP1 and eIF-4G, linked with more aggressive clinical behavior." (PMID 26275051, 2015). "A systematic approach addressing this question will be the subject of forthcoming in vitro and in vivo experiments, improving our knowledge about how specific mutations and the cancer cell origin affect the impact of inhibiting the MAPK and the PI3K/mTOR pathways." (PMID 26498922, 2015).